ENSG00000275427 (novel transcript)
Synonyms: LOC286083
Gene: Long non-coding RNA gene on chromosome 8 (1,296,034 to 1,302,607, reverse strand). Ensembl gene ENSG00000275427.
Diseases named in the same sentence as ENSG00000275427 in open-access papers:
ENSG00000275427 is named in the same sentence as 1 disease in open-access papers, as found by Europe PMC text mining. Sharing a sentence is not in itself a finding about the gene and the disease.
ENSG00000275427 shares sentences with these, for which no sentence is quoted: fragile X syndrome (1 paper).